PRSS2 (serine protease 2)
Diseases named in the same sentence as PRSS2 in open-access papers (continued):
Sharing a sentence is not in itself a finding about the gene and the disease.
tumor (19 papers, 2001 to 2025). "In localized prostate cancer (Series 1, n = 338), PRSS2 expression in tumor cells was associated with increased tumor cell proliferation (by Ki67 expression), and with increased VEGF-A." (PMID 36575174, 2022). "PRSS2 levels in tumor cells and in the associated stroma was significantly associated (Spearman’s correlation: Series 1, rho = 0.36, P < 0.0005; Series 2, rho = 0.45, P < 0.0005)." (PMID 36575174, 2022). "We found that in clinical primary tumor tissues, high levels of PRSS2 expression were associate with increased infiltration of FoxP3+ Tregs in radical prostatectomy specimens." (PMID 36575174, 2022). "Notably, these associations (Series 1–2) were found for PRSS2 levels in both tumor epithelium and when recorded separately in the stromal compartment." (PMID 36575174, 2022). "Proteinases such as MMP9 and PRSS2 are thought to form cascades that degrade tissue barriers and thus promote cell invasion and increased expression and secretion of these enzymes are associated with the metastatic capacity of tumor cells." (PMID 27711194, 2016). "Together, these findings provide preliminary evidence implicating PRSS2 in tumor–immune interactions." (PMID 41141930, 2025). "In this study, we compared the expression levels of PRSS2 between PTC tissues and adjacent non-tumor tissues and assessed its association with prognosis using data from the TCGA database." (PMID 41141930, 2025). "Here, we report the use of a proteomic screen to identify the tumor-secreted, metastasis-promoting, repressor of Tsp-1 as the serine protease PRSS2." (PMID 36575174, 2022). "Here, we identify a novel tumor-mediated mechanism that represses the expression of Tsp-1 in the TME via secretion of the serine protease PRSS2." (PMID 36575174, 2022). "In this report, we describe the identification of a novel stimulator of tumor growth and metastasis, the serine protease PRSS2." (PMID 36575174, 2022). "Given the well-established role of CD40 in antitumor immunity, this correlation suggests that PRSS2 may participate in the regulation of the tumor immune microenvironment." (PMID 41141930, 2025). "Its correlations with key immune-related genes, including TRBV, CD40, and TSC22D1, suggest that PRSS2 may be involved in tumor immune regulation, potentially contributing to improved clinical outcomes." (PMID 41141930, 2025). "In humans, PRSS2 is involved in inflammatory diseases as well as tumour growth." (PMID 40315186, 2025). "Collectively, despite its high expression in PTC, PRSS2 appears to be intricately involved in immune modulation, which may contribute to a more favorable tumor immune contexture and better clinical outcomes." (PMID 41141930, 2025). "Based on the observation that silencing PRSS2 in SUM159 cells significantly inhibited tumor growth, we asked whether this was due to the inability to repress Tsp-1 in the TME." (PMID 36575174, 2022). "Based on the ability of PRSS2 to reprogram the tumor microenvironment, this discovery could lead to the development of therapeutic agents that are indication agnostic." (PMID 36575174, 2022). "Thus, based on the paracrine mechanism of the anti-tumor activity of Tsp-1, a therapeutic strategy that disrupts its repression by PRSS2 should be indication agnostic." (PMID 36575174, 2022). "Given the profound inhibitory effects of silencing PRSS2 on tumor growth and progression, we examined whether modulating Tsp-1 expression in the TME had any effect on the tumor immune landscape." (PMID 36575174, 2022). "Silencing PRSS2 in tumor cells significantly attenuates tumor growth and metastasis." (PMID 36575174, 2022). "Higher ICI-4W expression of extracellular matrix (ECM) genes, including trypsinogens (PRSS1 and PRSS2) and matrix metalloproteases, and genes encoding cancer antigens (CTAG2, SAGE1, MAGEA1/A4/A10, POTEE, and PRAME) was significantly associated with ICI resistance and tumor growth during ICI-4W." (PMID 37433281, 2023).
tumor (continued). "In contrast, the association between high PRSS2 expression and favorable prognosis in PTC suggests that its oncogenic role may not be straightforwardly evident in the context of PTC, and that its biological function might be influenced by the specific tumor microenvironment and pathological state." (PMID 41141930, 2025). "Moreover, specific genetic deletion of the receptor for PRSS2, LRP1, in myeloid cells recapitulates the tumor-inhibitory effects of silencing PRSS2." (PMID 36575174, 2022). "To further examine the effects of PRSS2 on the immune microenvironment, we analyzed the infiltration of CD8 + and FoxP3 + T lymphocytes and their correlation with PRSS2 expression in patient tumor tissue samples." (PMID 36575174, 2022). "However, in the absence of Tsp-1, loss of PRSS2 does not inhibit tumor growth, indicating that the major role of PRSS2 in tumor growth is the paracrine-mediated repression of Tsp-1." (PMID 36575174, 2022). "Restriction enzyme digestion analyses indicated that PRSS3 is expressed by tumor-EC while PRSS1 and PRSS2 are not." (PMID 26318044, 2015).
cancer (10 papers, 2016 to 2025). A tumor composed of atypical neoplastic, often pleomorphic cells that invade other tissues. "Deletions of UGT2B17, PRSS2/PRSS3P2, and GSTT1/GSTTP2 were frequently observed in S1, and other reports indicate that these genes are frequently deleted in cancer cells." (PMID 27806083, 2016). "ROC curve analyses revealed that methylation status of each individual genes could significantly distinguish primary carcinoma from adjacent normal mucosa, as measured by AUC value (DLX6-AS1: 0.941; lnc-DPH5-1: 0.833; lnc-PRSS2-6: 0.913; lnc-RPS12-6: 0.916; lnc-SFRP4-2: 0.830; SOX21-AS1: 0.921)." (PMID 35127488, 2021).
digestive system tumors (1 paper, 2025). "Clinically, PRSS2 is significantly upregulated in various digestive system tumors (e.g., pancreatic, gastric, cholangiocarcinoma, and colorectal cancers), as well as in non-digestive system tumors such as breast, prostate, and ovarian cancers." (PMID 41141930, 2025).
PRSS2 also shares sentences with these, for which no sentence is quoted: acute pancreatitis (5 papers); infection (3); inflammatory bowel disease (2); ovarian tumors (2); tongue cancer (2); adenocarcinoma (1); benign ovarian tumours (1); diabetic nephropathy (1); gastric adenocarcinoma (1); liver cancer (1); lung adenocarcinoma (1); osteopetrosis (1); pancreatic disease (1); papillary thyroid carcinoma (1); pulmonary fibrosis (1); rheumatoid arthritis (1).